PCDHGA7 (protocadherin gamma subfamily A, 7)
Description:
Potential calcium-dependent cell-adhesion protein. May be involved in the establishment and maintenance of specific neuronal connections in the brain.
Synonyms: PCDH-gamma-A7
Tractability: Antibody: UniProt places it where antibodies can reach, with medium confidence; UniProt predicts a signal peptide or a membrane-spanning region; its Gene Ontology location is reachable by antibodies, with medium confidence.
Gene: Protein-coding gene on chromosome 5 (141,382,739 to 141,512,975, forward strand). Ensembl gene ENSG00000253537.
Subcellular location: Cell membrane
Subcellular location (Human Protein Atlas): Plasma membrane; Vesicles; Cytosol; Nucleoplasm
Gene Ontology:
Molecular function: cell adhesion molecule binding; calcium ion binding
Biological process: cell adhesion; homophilic cell-cell adhesion
Cellular component: plasma membrane; membrane
Genetic constraint (gnomAD): Loss-of-function variants: 44 observed, 61.95 expected, observed/expected ratio (o/e) 0.71, 90% interval 0.56 to 0.91. The upper end of that interval is the gene's LOEUF score, 0.91, which puts it in group 3 of 6, group 1 being the genes least tolerant of losing a copy. Missense variants: 1,266 observed, 1,263.6 expected, observed/expected ratio (o/e) 1, 90% interval 0.96 to 1.05. Synonymous variants: 516 observed, 537.55 expected, observed/expected ratio (o/e) 0.96, 90% interval 0.89 to 1.03.
Homologues: Orthologues: mouse Pcdhga7 (85% identical), rat Pcdhga7 (72% identical). Paralogues in human: PCDHGA6 (77% identical), PCDHGA10 (77% identical), PCDHGA8 (76% identical), PCDHGA4 (75% identical), PCDHGA5 (75% identical), PCDHGA3 (75% identical), PCDHGA12 (75% identical), PCDHGA1 (74% identical), PCDHGA2 (74% identical), PCDHGA9 (74% identical), PCDHGA11 (73% identical), PCDHGB1 (52% identical), and 49 more.